Y_RNA (Y RNA )
Gene: Miscellaneous RNA gene on chromosome 7 (116,909,877 to 116,909,964, reverse strand). Ensembl gene ENSG00000252115.
Homologues: Orthologues: chimpanzee Y_RNA (100% identical). Paralogues in human: Y_RNA (83% identical), RNY3 (82% identical), RNY3P1 (82% identical), Y_RNA (82% identical), Y_RNA (81% identical), Y_RNA (80% identical), Y_RNA (78% identical), RNY3P11 (77% identical), RNY3P14 (77% identical), RNY3P16 (77% identical), Y_RNA (77% identical), Y_RNA (76% identical), and 91 more.